METTL6 (methyltransferase 6, tRNA N3-cytidine)
Description:
S-adenosyl-L-methionine-dependent methyltransferase that mediates N(3)-methylcytidine modification of residue 32 of the tRNA anticodon loop of tRNA(Ser), including tRNA(Ser)(UGA) and tRNA(Ser)(GCU). Interaction with SARS1/SerRS is required for N(3)- methylcytidine methylation.
Synonyms: hMETTL6; MGC24132
Tractability: Small molecule: a structure with a bound ligand is known. PROTAC: ubiquitination databases record sites on it.
Gene: Protein-coding gene on chromosome 3 (15,381,061 to 15,440,566, reverse strand). Ensembl gene ENSG00000206562.
Subcellular location: Cytoplasm; Nucleus
Subcellular location (Human Protein Atlas): Vesicles
Gene Ontology:
Molecular function: enzyme binding; protein binding; tRNA (cytidine-3-)-methyltransferase activity
Biological process: tRNA C3-cytosine methylation; tRNA methylation; tRNA modification
Cellular component: cytoplasm; nucleus; tRNA methyltransferase complex
Genetic constraint (gnomAD): Loss-of-function variants: 24 observed, 30.37 expected, observed/expected ratio (o/e) 0.79, 90% interval 0.57 to 1.11. The upper end of that interval is the gene's LOEUF score, 1.11, which puts it in group 4 of 6, group 1 being the genes least tolerant of losing a copy. Missense variants: 304 observed, 342.74 expected, observed/expected ratio (o/e) 0.89, 90% interval 0.81 to 0.98. Synonymous variants: 109 observed, 122.91 expected, observed/expected ratio (o/e) 0.89, 90% interval 0.76 to 1.04.
Homologues: Orthologues: chimpanzee METTL6 (99% identical), macaque METTL6 (94% identical), pig METTL6 (92% identical), rabbit METTL6 (88% identical), guinea pig METTL6 (86% identical), mouse Mettl6 (86% identical), rat Mettl6 (85% identical), tropical clawed frog mettl6 (74% identical), zebrafish mettl6 (69% identical), Drosophila melanogaster CG34195 (53% identical), Caenorhabditis elegans metl-6 (40% identical). Paralogues in human: METTL2B (43% identical), METTL2A (42% identical), METTL8 (40% identical).
Diseases named in the same sentence as METTL6 in open-access papers:
METTL6 is named in the same sentence as 17 diseases in open-access papers, as found by Europe PMC text mining. Sharing a sentence is not in itself a finding about the gene and the disease. The quoted sentences say what the papers report.
hepatocellular carcinoma (6 papers, 2021 to 2026). A malignant tumor that arises from hepatocytes. "The m3C modification is catalyzed by the methyltransferase-like protein 2 and 6 (METTL2 and METTL6) and human METTL6 has been associated with regulating cellular growth, ribosomal occupancy, and pluripotency in hepatocellular carcinoma (HCC)." (PMID 35327975, 2022). "METTL6 is essential for the maintenance of stem cell self-renewal and the promotion of hepatoma cell growth." (PMID 38824202, 2024). "Depletion of METTL6 in hepatocellular cancer cells (HCCs) affects translation of mRNAs related to cell proliferation and growth." (PMID 33564819, 2021). "In hepatocellular carcinoma (HCC), METTL6 depletion inhibits cell growth, colony formation, migration, invasion, and cell adhesion and reduces the expression levels of cell adhesion proteins such as ITGA1, SPON1, and CLDN14." (PMID 41501031, 2026).
breast carcinoma (5 papers, 2016 to 2024). "METTL6 was identified as a marker of the proliferation of luminal breast cancers, but the biological role of this RNA-modifying methyltransferase is not well understood." (PMID 34785643, 2021). "Importantly, patients with low METTL6 levels in HCC exhibit increased survival rates, aligning with previous findings in human breast cancer cells, indicating a context-dependent role for METTL6 in cell growth across various cell types." (PMID 38476632, 2024). "Similarly, while individual deletion of METTL2 or METTL6 had a modest effect on growth of MCF7 human breast cancer cells, the further siRNA-mediated depletion of either METTL6 in the METTL2 KO cells, or knockdown of METTL2 in the METTL6 KO cells strongly suppressed cell proliferation." (PMID 38982125, 2024).
liver cancer (2 papers, 2022 to 2024). An epithelial or non-epithelial malignant neoplasm that arises from the liver. "Recently, it is demonstrated that the deletion of METTL6 showed a significant inhibition on the proliferation of liver cancer cell lines and the high expression of METTL6 in malignant patients tended to indicate a poor prognostic." (PMID 36266694, 2022). "Downregulation of METTL6 has been shown to inhibit liver cancer cell proliferation and invasion." (PMID 38982125, 2024).
breast invasive carcinoma (1 paper, 2024). "The N3-methylcytidine (m3C) gene, METTL2A, is highly expressed in breast invasive carcinoma (BRCA), and differential analysis showed that METTL2A was differentially expressed in cancer and paracancerous tissues more strongly than METTL6 and METTL8." (PMID 39289775, 2024).
breast tumors (1 paper, 2024). "METTL6 acts as an oncogene in luminal breast tumors and hepatocarcinoma, and METTL2A also seems to play a role in breast cancer." (PMID 38918637, 2024).
endometrial carcinoma (1 paper, 2022). A malignant tumor arising from the epithelium that lines the cavity of the uterine body. "The frequency of METTL6 alteration is the highest in BLCA (4.5%), Uterine Corpus Endometrial Carcinoma (3%), and KIRC (2.5%)." (PMID 36266694, 2022).
glioma (1 paper, 2024). A benign or malignant brain and spinal cord tumor that arises from glial cells (astrocytes, oligodendrocytes, ependymal cells). "Results revealed that TRMT2B, TRMT11, METTL8, TRMT6, and TRUB2 were upregulated in glioma, while METTL6 was downregulated." (PMID 38824202, 2024). "In glioma cells, it was observed that the expression of genes related to MRM, like GTPBP3, METTL2A, METTL6, METTL8, NSUN4, and TRMT61A, showed positive correlation with the expression of HAVCR2, PVR, TNFRSF25 and TNFSF15 as revealed by scRNA-seq analysis." (PMID 38824202, 2024). "We observed the high expression levels of METLL8, METLL2A, TRMT112, METTL2B, GTPBP3, METTL6, and NSUN4 in cells in the S, G2M, and G1 phases, which were similar for astrocytes, glioma cells, and oligodendrocytes." (PMID 38824202, 2024). "The expression of HAVCR2, PVR, TNFRSF25, and TNFSF15 showed a positive correlation with the expression of numerous MRM-related genes like GTPBP3, METTL2A, METTL6, METTL8, NSUN4, and TRMT61A in glioma cells." (PMID 38824202, 2024).
lung adenocarcinoma (1 paper, 2025). A carcinoma that arises from the lung and is characterized by the presence of malignant glandular epithelial cells. "METTL1, METTL3, METTL4, METTL5, METTL6 and METTL13 were associated with poor prognosis in various tumors including liver hepatocellular carcinoma (LIHC), breast invasive carcinoma (BRCA), and lung adenocarcinoma (LUAD)." (PMID 41194259, 2025).
lung carcinoma (1 paper, 2024). "In lung cancer, the loss of METTL6 can reduce the sensitivity of lung cancer cells to cisplatin." (PMID 38943267, 2024).
male infertility (1 paper, 2025). The inability of the male to effect fertilization of an ovum after a specified period of unprotected intercourse. "RNA‐seq and m6A‐seq analyses revealed that deletion of either Mettl6 or Ythdc1 disrupted the gene expression related to chromosome organisation and segregation, ultimately leading to male infertility." (PMID 39614650, 2025).
ovarian carcinoma (1 paper, 2025). A malignant neoplasm originating from the surface ovarian epithelium. "The downregulation of METTL6 had little effect on circMETTL6 expression, cell growth, migration, and invasion in ovarian cancer cells." (PMID 39899667, 2025). "Collectively, these results indicate that circMETTL6 plays a tumor‐suppressive role in ovarian cancer in vitro and in vivo, which is functionally independent of its parental METTL6 transcript." (PMID 39899667, 2025).
ovarian tumors (1 paper, 2025). "In this study, we performed differential expression analysis of circRNAs between ovarian tumors and normal tissues and identified a novel circRNA, circMETTL6, derived from methyltransferase‐like protein 6 (METTL6)." (PMID 39899667, 2025).
Thyroid carcinoma (1 paper, 2022). "In contrast, there was down-regulation of these four genes in Kidney Chromophobe (KICH), Kidney renal clear cell carcinoma (KIRC), and Thyroid carcinoma Compared to METTL8, the other three genes (METTL2A, METTL2B and METTL6) exhibited a more homogenized co-expression in various cancer types." (PMID 36266694, 2022).
tumor (10 papers, 2021 to 2025). "METTL6 was highly expressed in HCC tissues compared with adjacent non-tumor tissues, which was closely associated with poorer survival outcomes in HCC patients." (PMID 39289775, 2024). "METTL6 functions as a m3C methyltransferase, exerting regulatory control over tumor cell proliferation." (PMID 39019857, 2024). "Additionally, METTL6 and TRMT11 encode tRNA methyltransferases that regulate transcript processing and promote tumor cell proliferation." (PMID 40561176, 2025). "Interestingly, expression of METTL2A, METTL2B, and METTL6 mRNA is elevated in most tumor types compared with corresponding normal tissues and is associated with poor prognosis." (PMID 38982125, 2024). "In addition, we explored the relationship between the TRGs risk model and TME, and revealed the strong association of METTL6, LCMT1, GSTZ1, ADH4, and ADH1A with the tumor immune infiltration and immune checkpoints." (PMID 36341373, 2022). "Multi-omics analyses revealed consistently elevated expression of AHCY, BUD23, LCMT1, MARS1, METTL6, SCLY and SEPHS1 in various tumor types." (PMID 41441975, 2025). "The differential expression analysis of METTL2A, METTL2B METTL6 and METTL8 was conducted between tumor tissue and normal tissue in 24 different cancer types." (PMID 36266694, 2022). "Interestingly, compared with METTL8 and METTL6, differential expression of METTL2A in BRCA tumor tissues and adjacent normal tissues was more significantly." (PMID 36266694, 2022).
cancer (7 papers, 2021 to 2025). A tumor composed of atypical neoplastic, often pleomorphic cells that invade other tissues. "Of the 30 METTLs, expressions of eight (METTL1, METTL7B, METTL5, NTMT1, METTL2A, METTL2B, EEF1AKNMT, METTL6) were significantly (FDR < 0.05) associated with unfavorable overall survival across cancers." (PMID 34285249, 2021). "Another cancer genomics study identified METTL6 as one of eight essential genes highly amplified in patients with luminal-type breast cancer." (PMID 38982125, 2024). "The m3C associated genes showed aberrant expression in 17 cancer types for METTL2A, 15 cancer types for METTL2B, 14 cancer types for METTL6 and 13 cancer types for METTL8." (PMID 36266694, 2022). "METTL6 is a transfer RNA methyltransferase, whose function and mechanism in cancer development are poorly understood." (PMID 36341373, 2022). "There were several studies figuring out the vital important relationship between METTL6 and the prognostic of malignant tumor patients." (PMID 36266694, 2022). "Consistently, the silence of METTL6 and LCMT1 decreased cancer cell migration, and depletion of GSTZ1 and ADH4 increased the cancer cell migration ability." (PMID 36341373, 2022).
METTL6 also shares sentences with these, for which no sentence is quoted: developmental delay (1 paper); renal carcinoma (1).